ELOVL5 (ELOVL fatty acid elongase 5)
Diseases named in the same sentence as ELOVL5 in open-access papers (continued):
Sharing a sentence is not in itself a finding about the gene and the disease.
normal tension glaucoma (2 papers, 2012 to 2018). "Another Japanese group carried out a separate GWAS, identifying S1 RNA binding domain 1 (SRBD1) and ELOVL fatty acid elongase 5 (ELOVL5) as new susceptibility genes for both normal tension glaucoma (NTG) and POAG (with the most highly associated SNPs being rs3213787 in SRBD1 and rs735860 in ELOVL5)." (PMID 22761751, 2012).
Allergy (1 paper, 2019). An allergy is an immune response or reaction to substances that are usually not harmful. "We investigated whether DNA-M and expression of the FADS1/2 and ELOVL5 genes were associated with allergy in children and gestational fish intake." (PMID 31244960, 2019). "The association between induced FADS1/2 and ELOVL5 DNA-M and reduced gene expression due to gestational fish intake provide a mechanistic explanation of the previously observed association between maternal LCPUFA intake and allergy development in early childhood." (PMID 31244960, 2019).
amyotrophic lateral sclerosis (1 paper, 2024). Amyotrophic lateral sclerosis (ALS) is a neurodegenerative disease characterized by progressive muscular paralysis reflecting degeneration of motor neurons in the primary motor cortex, corticospinal tracts, brainstem and spinal cord. "A more comprehensive analysis indicates that upregulated proteins (ELOVL5, ELOVL7, TECR, HSD17B4, ACSL1, HACD2, and CBR4) are significantly enriched within the pathways of oxidative phosphorylation and metabolic pathways pertinent to amyotrophic lateral sclerosis." (PMID 39335340, 2024).
autosomal dominant cerebellar ataxia (1 paper, 2023). A clinically and genetically heterogeneous group of neurodegenerative diseases characterized by a slowly progressive ataxia of gait, stance and limbs, dysarthria and/or oculomotor disorder, due to cerebellar degeneration in the absence of coexisting diseases. "Alongside ELOVL5, ELOVL4 is currently the only other elongase involved in an autosomal dominant cerebellar ataxia: SCA34." (PMID 37199746, 2023).
autosomal recessive retinitis pigmentosa (1 paper, 2021). Autosomal recessive retinitis pigmentosa (RP) is an autosomally recessive inherited retinal dystrophy leading to progressive loss of the photoreceptors and retinal pigment epithelium and resulting in blindness usually after several decades. "Consistently, no mutations in Elovl5 were observed in patients with autosomal recessive retinitis pigmentosa." (PMID 33465374, 2021).
breast tumors (1 paper, 2022). "In accordance with this finding, decrease of Elovl5 expression was more pronounced in ER+ breast tumors from patients with metastases in lymph nodes." (PMID 36056008, 2022). "Moreover, we were able to show an increase of TGFBR1 and TGFBR2 mRNA expression in breast tumors from Elovl5−/− mice compared to tumors from Elovl5+/+." (PMID 36056008, 2022). "In addition, we analyzed TAG content in breast tumor tissues in which Elovl5 expression was lower compared to their paired non-tumoral counterparts from patients with different cancer subtypes." (PMID 36056008, 2022).
diabetic nephropathy (1 paper, 2025). "The present study showed that AARS1 induced the lactylation of H3K18 and STAT1 to regulate ELOVL5 transcription, thus triggering ferroptosis in a diabetic nephropathy model." (PMID 40987895, 2025).
eczema (1 paper, 2019). "A total of 39 CpG sites spanning the genomic region of the FADS cluster and 27 CpG sites in ELOVL5 were analyzed for association with wheeze and eczema." (PMID 31244960, 2019). "ELOVL5 rs2397142 was significantly associated with eczema (P = 0.011) and methylation at cg11748354 and cg24524396 (P < 0.001 and P = 0.036, respectively)." (PMID 31244960, 2019). "Among these, the ELOVL5 variant rs2397142 was associated with eczema (P = 0.011)." (PMID 31244960, 2019). "Also, methylation levels of cg18564099 in ELOVL5 showed an association with eczema (P = 0.046)." (PMID 31244960, 2019). "Finally, rs2397142 in ELOVL5 showed significant association with eczema in this study." (PMID 31244960, 2019).
glioblastoma (1 paper, 2023). The most malignant astrocytic tumor (WHO grade IV). "Elovl5 may have both protumor and antitumor properties in glioblastoma." (PMID 37046844, 2023).
Glucose intolerance (1 paper, 2019). Glucose intolerance (GI) can be defined as dysglycemia that comprises both prediabetes and diabetes. "Specifically, previous studies in mice have reported a relationship between low ELOVL5 activity in the liver and glucose intolerance and insulin resistance." (PMID 31690730, 2019).
HCMV infection (1 paper, 2021). "ELOVL5 protein levels increase following HCMV infection independently of PERK, consistent with an increase in lipids with PUFA tails in infected PERK-KO cells." (PMID 33947752, 2021). "Using AD169, we previously demonstrated that HCMV infection increases ELOVL5 and ELOVL7 transcripts, ELOVL7 protein levels, FA elongation, VLCFA synthesis, the abundance of PLs with SFA/MUFA tails, and the levels of PERK protein." (PMID 33947752, 2021). "HCMV infection also increases ELOVL5 gene expression and protein levels by 2.5-fold at 72 and 96 hpi in HFF cells." (PMID 33947752, 2021). "Additionally, the protein levels of ELOVL5, which elongates PUFAs, are increased by HCMV infection through a PERK-independent mechanism." (PMID 33947752, 2021). "This action balances the elongation of PUFAs made by ELOVL5, which HCMV infection promotes through an unknown PERK-independent mechanism." (PMID 33947752, 2021). "We conclude that PERK is necessary for HCMV infection-related increases in ELOVL7, but not ELOVL5, protein levels." (PMID 33947752, 2021). "Following HCMV infection, PERK regulates lipid metabolism by promoting ELOVL7, but not ELOVL5." (PMID 33947752, 2021).
hereditary ataxia (1 paper, 2018). An instance of an atactic disorder that is caused by an inherited genomic modification in an individual. "The interaction between ELF2,ATXN2, and ELOVL5 genes found suggests that the regulation of expression in these genes could potentially be a shared mechanism in hereditary ataxias." (PMID 29628936, 2018).
Hypercholesterolemia (1 paper, 2025). An increased concentration of cholesterol in the blood. "We investigated whether an alteration of the PUFA homeostasis triggered by a combined Lpcat3/Elovl5 deficiency in macrophages would affect the atherosclerotic process in a mouse model of hypercholesterolemia." (PMID 40345182, 2025).
ischemic stroke (1 paper, 2025). A stroke disorder caused by obstruction of blood flow to the brain, due to thrombotic (local blood clot formation) or embolic (due to a blood clot or other material traveling from another site) event. "Furthermore, we performed Mendelian randomization analysis to explore the potential causal relationship between the expression levels of LPCAT3 and ELOVL5 and the incidence of ischemic stroke in humans." (PMID 40345182, 2025).
liver disease (1 paper, 2025). "The rats' model of parenteral nutrition-associated liver disease was used to study changes in the ER stress markers, Elovl5 and Ptbp3, and their in vitro role was determined." (PMID 41209571, 2025). "We confirmed these findings in vitro by establishing that Elovl5 and Ptbp3 play a role in parenteral nutrition-related liver disease by modulating the ROS generation and cell death." (PMID 41209571, 2025).
prostate tumour (1 paper, 2024). "In PCa, it was recently shown that fatty acid chain elongation via ELOVL5 promotes prostate tumour growth." (PMID 38216720, 2024).
renal carcinoma (1 paper, 2023). A carcinoma arising from the epithelium of the renal parenchyma or the renal pelvis. "The use of CRISPR/Cas9-mediated knockout to target ELOVL5 inhibits AKT Ser473 phosphorylation and suppresses renal cancer cell invasion by downregulating chemokine (C–C motif) ligand-2 through the AKT-mTOR-STAT3 signaling pathway." (PMID 37981715, 2023).
renal cell carcinoma (1 paper, 2023). "In renal cell cancer, higher levels of ELOVL5 correlate with poor clinical prognosis, and ELOVL5 seems to lead to cancer cell proliferation and invasion." (PMID 36970499, 2023).
retinitis pigmentosa (1 paper, 2013). Retinitis pigmentosa (RP) is an inherited retinal dystrophy leading to progressive loss of the photoreceptors and retinal pigment epithelium and resulting in blindness usually after several decades. "ELOVL5 is a fatty acid condensing enzyme involved in the biosynthesis of long-chain polyunsaturated fatty acids, and is one of the candidate genes for retinitis pigmentosa." (PMID 24040232, 2013).
tumor (29 papers, 2011 to 2025). "While reduction in ELOVL5 expression has been linked to worsened prognosis in breast estrogen receptor-positive cancer patients, its role in behavior regulation is still unclear." (PMID 37663250, 2023). "ESTIMATE score demonstrated that high expression levels of LIFR, ARHGAP24, and ELOVL5 were significantly associated with lower tumor purity, whereas CBX3 exerted an inverse effect." (PMID 33463006, 2021). "The ESTIMATE score, combination of stromal and immune score, indicated that high expression levels of LIFR, ARHGAP24, and ELOVL5 were significantly associated with lower tumor purity, whereas CBX3 exerted an inverse effect." (PMID 33463006, 2021). "In this work, to study the changes in model tumor cells associated with the changes in the expression of the ELOVL5 and IGFBP6 genes, we decided to knock down the genes under consideration using RNA interference." (PMID 34149804, 2021). "These include proteins involved in vesicle transport, such as Rab10, a pathway closely linked to ARL5B-mediated lysosomal trafficking, as well as ELOVL5(elovl fatty acid elongase 5), which has been implicated in tumor immunity through immunometabolic regulation." (PMID 41451209, 2025). "Overexpression of ELOVL2 and ELOVL5 in para-tumor tissue demonstrates the production of ARA, which is necessary for the generation of signaling and inflammatory lipids." (PMID 39145825, 2025). "The expression levels of key enzymes involved in unsaturated fatty acid metabolism (Fads2, Elovl5, Fads1, Elovl2) were significantly altered in the liver and tumor tissues of the HUFA-gavaged mice." (PMID 39941731, 2025). "Immunofluorescence analysis confirmed the coexpression of CXCR2, CXCL15, FAS, and ELOVL5 within the tumours." (PMID 41163221, 2025). "Ischemia very interestingly appears to slowly breach through this coping mechanism by causing a decrease in tumor survival-critical proteins such as NUDT1, ELOVL5, HPGDS or DZIP3." (PMID 39327466, 2024). "The authors also described the correlation of ELOVL5 expression with tumor stage and relapse-free survival." (PMID 36970499, 2023). "ELOVL5 expression can be higher in a GBM tumor as a result of hypoxia, as shown by our experiments with U87 MG line cells." (PMID 36765904, 2023). "The ELOVL3 expression in the tumor core was negatively correlated with ELOVL5 and ELOVL6 expressions in the enhancing tumor region." (PMID 36291290, 2022). "At the same time, the expression of ELOVL2 and ELOVL5 in the enhancing tumor region in women negatively correlated with their age." (PMID 36291290, 2022). "In the enhancing tumor region and tumor core, the ELOVL5 expression in the women was lower than in the men (enhancing tumor region—p = 0.02; tumor core—p = 0.04)." (PMID 36291290, 2022). "The surface of the aggregated tumor lesions at 180 days was lower in Elovl5−/− than in Elovl5+/+ mice." (PMID 36056008, 2022). "In these 22 days, the mean aggregated tumor surface increased 11.6-fold in Elovl5+/+ mice and only 7.4-fold in Elovl5−/− mice." (PMID 36056008, 2022). "Next, we assessed the effect of Elovl5 overexpression in tumor growth by grafting 4T1 cells stably overexpressing Elovl5 or control 4T1 cells in the fourth mammary fat pad of female Balb-c mice." (PMID 36056008, 2022). "Here, significantly increased mRNA levels of ELOVL5 were found in tumor tissue, which corresponded with increased calculated ELOVL2/5 activity." (PMID 34206240, 2021). "Further research will help shed light on the detailed molecular mechanisms responsible for the observed changes in tumor cell properties resulting from a decreased expression of the ELOVL5 and IGFBP6 genes." (PMID 34149804, 2021). "For instance, ELOVL5, another enzyme in this family, has been shown to alter mitochondrial morphology and function, leading to increased reactive oxygen species production and subsequent suppression of PCa cell proliferation, tumor growth, and metastasis." (PMID 40552308, 2025).
tumor (continued). "In contrast, tumor levels of Elovl5 were significantly increased in response to ARA gavage." (PMID 39941731, 2025). "Elovl5 promotes ferroptosis by increasing AA synthesis in a variety of tumor cells." (PMID 41285716, 2025). "Additionally, ELOVL5 is known to be highly expressed in both primary and metastatic tumours, with numerous studies suggesting that downregulation of ELOVL5 has profound phenotypic effects on PC cells." (PMID 36991255, 2023). "This may explain the correlation between the ELOVL5 expression in the enhancing tumor region and BMI in all patients." (PMID 36291290, 2022). "Additionally, the ELOVL5 expression in the tumor core was positively correlated with the ELOVL6 expression in the enhancing tumor region." (PMID 36291290, 2022). "Additionally, the expression of ELOVL2 and ELOVL5 in the enhancing tumor region negatively correlated with age in the women." (PMID 36291290, 2022). "In the tumor, there was decreased expression of ELOVL5 in the women compared to the peritumoral area (enhancing tumor region—p = 0.015; tumor core—p = 0.005), and an increased expression of ELOVL5 in the men (enhancing tumor region—p = 0.03; tumor core—p = 0.055)." (PMID 36291290, 2022). "Our results showed that Elovl5 expression increased the 4T1 tumor growth." (PMID 36056008, 2022). "In particular, this included genes involved in secretory pathways, lipid and sugar metabolism (such as, UGDH, SORD, GLUD1, ELOVL5, ASCL3, UAP1), but also genes implicated in tumor progression and metastasis with functions in cell survival, proliferation and adhesion (EHF, ELL2, TPD52, MAFB, SGK)." (PMID 21829708, 2011). "However, we observed a slight delay in tumor onset in Elovl5−/− compared to Elovl5+/+ mice which could explain the difference in tumor surface." (PMID 36056008, 2022). "Thus, the increase in MMP1 and MMP3 expression observed after the knockdown of the ELOVL5 and IGFBP6 genes is consistent with the hypothesis that ELOVL5 and IGFBP6 are associated with tumor metastatic potential." (PMID 34149804, 2021). "Regardless of luminal subtype (A/B), LM cells had increased expression of ELOVL5, EFHD1, NEK10, LYPD6 and NOVA1, among others, relative to the tumor cells." (PMID 39478117, 2024). "We showed that the expression of ELOVL2, ELOVL5, and ELOVL6 in the GBM tumor was lower in women than in men." (PMID 36291290, 2022). "In the men, the expression of the elongases positively correlated with BMI —in particular, the ELOVL2 expression in the peritumoral area and tumor core, and ELOVL5 and ELOVL6 expressions in the enhancing tumor region." (PMID 36291290, 2022). "There was a positive correlation between ELOVL4, ELOVL5, ELOVL6, and ELOVL7 expressions in the GBM tumor." (PMID 36291290, 2022). "As PGE2 is responsible for radioresistance and temozolomide (TMZ) resistance, the enzymes involved in the synthesis of arachidonic acid C20:4n-6—in particular, Elovl5 and Fads2/D6D—are also responsible for the resistance to GBM anti-tumor therapy." (PMID 36291290, 2022). "The same correlation was also found in men, i.e., BMI vs. ELOVL5 and ELOVL6 expressions in the enhancing tumor region and the ELOVL2 expression in the tumor core." (PMID 36291290, 2022). "This study examines the expression of elongases ELOVL1, ELOVL2, ELOVL3, ELOVL4, ELOVL5, ELOVL6, and ELOVL7 in GBM tumor samples from 28 patients (16 men and 12 women), using a quantitative real-time polymerase chain reaction (qRT-PCR)." (PMID 36291290, 2022). "Overall, the transcriptional downregulation of ELOVL5, MTERF1 and ZNF606 shows potentially beneficial effect for the tumor cells." (PMID 28931069, 2017). "Furthermore, we examined the expression levels of ACADM, FASN, ACC1, ELOVL5, and FABP1 in primary tumor tissues and TD tissues through IHC methods." (PMID 39495391, 2024).
tumor (continued). "Additionally, the ELOVL3 expression in the tumor core was positively correlated with the ELOVL5 expression from the enhancing tumor region and negatively correlated with the ELOVL2 expression from the enhancing tumor region." (PMID 36291290, 2022). "Additionally, the ELOVL1 expression in the tumor core was positively correlated with ELOVL4, ELOVL5, ELOVL6, and ELOVL7 expressions." (PMID 36291290, 2022). "No relation was observed between ELOVL5 staining intensity of neoplastic cells and tumor stage, TNM staging or relapse-free-survival." (PMID 28931069, 2017). "Specifically, tumor cells educated TANs to overexpress SPP1, GBP1, and ELOVL5, which subsequently activated three key mechanisms: promoting angiogenesis (SPP1-NF-κB-HIF/VEGF), immunosuppression (GBP1-NF-κB-PD-L1), and dysregulated oxidative lipid metabolism (ELOVL5-NF-κB), leading to poor prognosis." (PMID 41313078, 2025). "While previous studies established ELOVL5’s role in promoting ferroptosis through arachidonic acid (AA) synthesis in tumor cells, our work demonstrates for the first time ELOVL7 (rather than ELOVL5) as the dominant elongase in podocyte ferroptosis." (PMID 41285716, 2025). "The expression of the negative genes (ELOVL5, PTGER3, KIAA1324, and CYBRD1) in tumors was lower than that in normal and tumor-adjacent tissues." (PMID 36341435, 2022). "In the women, there was a negative correlation between ELOVL5 and ELOVL6 expressions in the GBM tumor and BMI." (PMID 36291290, 2022).